S100A4 (S100 calcium binding protein A4)
Diseases named in the same sentence as S100A4 in open-access papers (continued):
Sharing a sentence is not in itself a finding about the gene and the disease.
tumor (continued). "Percentages of CD11c+ dendritic cells, B220+ B cells, CD4+ and CD8+ T cells, forkhead box protein (FoxP3+) regulatory T cells, and NK1.1+ natural killer (NK) cells were the same in spleens of MCA205 tumor-bearing WT and S100A4−/− mice." (PMID 29556233, 2018). "The tumors in the WT mice grew rapidly, whereas tumor development was severely impaired in the S100A4−/− mice." (PMID 29449540, 2018). "S100A4 is commonly used as a mesenchymal cell marker and promotes tumor metastasis dependent on the interaction with RAGE." (PMID 28212564, 2017). "In the majority of CRC tumor specimens Wnt signalling is known to be dysregulated and therefore constitutively active, whereas S100A4 is a downstream effector molecule of this signalling." (PMID 28423501, 2017). "The expression of S100A4 in tumor cells is strongly correlated with an aggressive metastatic phenotype." (PMID 29204268, 2017). "Overall, in a cohort of CRC patient tumor specimens, a significant downregulation of miR-520c-3p expression and upregulation of S100A4 mRNA expression was observed." (PMID 28423501, 2017). "S100A4 potentially enhances tumor metastasis in pre-existing tumorigenic mouse models of breast cancer." (PMID 28051137, 2017). "Activated “host” cells (fibroblasts, immunocytes, vascular cells, among others) secrete S100A4 into the extracellular space in various non-tumor human disorders, where it executes its biological functions by interacting with intracellular target proteins." (PMID 29204268, 2017). "Several studies have indicated that S100A4 promotes tumor cell migratory phenotype and that the reduced S100A4 levels decrease tumor cell migration as well as inhibit tumor cell EMT." (PMID 29069865, 2017). "S100A4, as an extracellular protein, can stimulate angiogenesis and attract immune cells to the growing tumor-lesions as well as promote the secretion of various cytokines and growth factors into the tumor microenvironment." (PMID 29069865, 2017). "Our findings in this study strongly support miR-520c-3p as tumor suppressor miRNA which is downregulated in CRC and also causes upregulation of its target proteins such as the metastasis-associated gene S100A4 in tumor tissue." (PMID 28423501, 2017). "In this review, we summarize the role of S100A4 in fibrosis, inflammation, immune response, neuroprotection, angiogenesis, and some common non-tumor diseases as well as its possible involvement in molecular pathways and potential clinical value." (PMID 29204268, 2017). "The original cloning efforts reported S100A4 to be a highly expressed transcript in cells with growth-related transformation, metastatic tumor cells, and in cells undergoing conversion from an epithelial to mesenchymal phenotype." (PMID 29204268, 2017). "S100A4, an important member of S100 family proteins, functions to increase the tumor progression and metastasis." (PMID 29069865, 2017). "The S100A4 protein is known to be secreted by tumor and stromal cells and to support tumorigenesis by stimulating angiogenesis." (PMID 28686225, 2017). "Taken together, these methylation analysis and gene expression studies revealed that due to epigenetic downregulation of miR-520c-3p its post-transcriptional target S100A4 was upregulated in CRC tumor specimens." (PMID 28423501, 2017). "S100A4 involves in inflammation processes by attracting T-cells to the primary tumor and the pre-metastatic niche." (PMID 29069865, 2017). "S100A4/MACC1 cluster in circulating tumor cells from patients with metastatic CRC was shown to be closely related to progression-free and overall survival rates." (PMID 29069865, 2017). "Later, transgenic mice, expressing high levels of S100A4, were shown to promote neoplasia related to the expression of the MMTV-neu transgene." (PMID 29069865, 2017). "S100A4 participates in the molecular signal-network of the tumor milieu that contributes to cancer metastasis through the modulation of both primary tumor and pre-metastatic niche." (PMID 29069865, 2017).
tumor (continued). "Niclosamide-treated CRC cells in vitro was able to reduce the levels of S100A4 mRNA and protein, and subsequently inhibit tumor cell migration, invasion, proliferation, and colony formation." (PMID 29069865, 2017). "The cooperation of RhoA/MMP-9 and Cdc-42/MT1 MMP pathways can form invadopodia of tumor cells activated by nuclear S100A4." (PMID 29069865, 2017). "The knockdown of S100A4 using RNAi in ESCC cells inhibited tumor cell proliferation, invasion, and metastasis, partly through the activation of MMP-2 and the inhibition of E-cadherin." (PMID 29069865, 2017). "S100A4 expression is transcriptionally regulated by β-catenin and both were found to be highly expressed at the invasive margin of a tumor." (PMID 28423501, 2017). "Numerous studies have indicated that the S100A4-mediated epithelial–mesenchymal transition plays a vital role in the occurrence and development of various non-tumor pathophysiologies." (PMID 29204268, 2017). "Further, co-injection of S100A4-negative tumor cells with S100A4 protein or with S100A4-positive fibroblasts promoted tumor metastatic capability, indicating that S100A4 can promote cancer progression and metastasis." (PMID 29069865, 2017). "Our results link pathways important for tumor progression and metastasis: the Wnt signaling pathway and S100A4, which regulates motility and invasiveness." (PMID 27331819, 2016). "Several studies in epithelial and mesenchymal tumours revealed a correlation between extracellular S100A4 and metastasis." (PMID 26928771, 2016). "In consistency with the presented model, in vivo overexpression of S100A4 led to a significant increase in tumour growth and vascularization in a human melanoma xenograft M21 model." (PMID 27278648, 2016). "Further, the expression of S100A4 in the advancing tumor front can be used as an independent indicator for overall survival." (PMID 27331819, 2016). "Previously, knockdown experiments have shown that inhibition of S100A4 expression suppresses the metastatic capacity of S100A4-expressing tumor cells in animal models." (PMID 27354287, 2016). "Previous studies have shown that S100A4 expression can upregulate the matrix metalloproteinases (MMPs), which play critical role in tumor metastasis through degradation of extracellular matrix (ECM), including MMP-9, MMP-13, and MMP-2." (PMID 26903691, 2016). "Here, higher concentrations of S100A4 increased cell growth as well as tumour growth after 5 or 14 days respectively." (PMID 26928771, 2016). "S100A4 can also activate NF-κB, thus stimulating a pathway that promotes proliferation and cell survival in multiple tumor types." (PMID 27127879, 2016). "In fact these data paved the ground for analyzing the anti-tumor and anti-metastatic efficacy of sulindac in the context of S100A4, as one attractive target of the Wnt signaling pathway." (PMID 27331819, 2016). "The mechanistic studies via quantitative analysis of global proteome in xenograft tumours revealed that some metastasis-associated proteins, including S100A4, MARCKSL1 and BAG4 were increased in ELL(C595A) xenograft tumours compared to the control tumours." (PMID 27009366, 2016). "A very recent aspect of S100A4-dependent mechanisms at the plasma membranes of tumor cells has been published by Jaiswal and colleagues." (PMID 27331819, 2016). "The role of S100A4 in tumor progression and metastasis via induction of EMT has been confirmed in many types of cancers, including CRC." (PMID 27331819, 2016). "Taken together, the reduction of S100A4 expression, either in the tumor itself or in its environment, has been proven to reduce the metastatic potential of CRC, shown by decreased cell motility in vivo, as well as in less metastasis formation in vivo." (PMID 27331819, 2016). "Again, S100A4 expression in primary tumors was higher in patients with metastases after tumor resection, and both the overall and metastasis free survival differed significantly, depending on the S100A4 expression." (PMID 27331819, 2016).
tumor (continued). "There was a weak relationship between S100A4 nuclear staining and male gender, advanced T stage, and poor tumor differentiation." (PMID 27273130, 2016). "The cellular functions of S100A4 were mainly characterized in cancer, promoting tumor progression and metastasis formation, reviewed by Boye and Mælandsmo, and recently by Bresnick and colleagues." (PMID 27331819, 2016). "Then, using a commercially available antibody, anti-S100A4, we validated upregulation of S100A4 in pHAGE-ELL(C595A) tumours." (PMID 27009366, 2016). "S100A4 is also secreted into the intercellular fluid—by the tumor cell itself or by cells in the local tumor environment—and can exert multiple functions by interaction with receptors like RAGE." (PMID 27331819, 2016). "Our network approach also identified a highly ranked target, S100A4, that turned out to be specific to a single tumor line." (PMID 27354287, 2016). "Very recently, Barbazan and colleagues reported the prognostic relevance of a S100A4/MACC1 cluster in circulating tumor cells for progression-free and overall survival of patients with metastatic CRC." (PMID 27331819, 2016). "Today, S100A4 expression in tumor tissue is a valid and valuable biomarker for determining the risk for metastasis formation of CRC patients, and much effort is made to evaluate S100A4 expression in tumors as a predictor for therapy response." (PMID 27331819, 2016). "S100A4/RAGE signaling has been linked to the pro-migratory, invasive, and metastatic characteristics of several tumor types, including thyroid, prostate, and colorectal." (PMID 27598148, 2016). "Paralleling this clinical trial, translational research is performed, e.g., determining S100A4 expression in tumor tissues and metastases, and monitoring treatment success by quantifying the circulating S100A4 transcripts in patient blood." (PMID 27331819, 2016). "These in vitro and in vivo experiments demonstrate that S100A4-mediated tumor progression and metastasis formation, driven by β-catenin signaling, can be mitigated with administration of sulindac." (PMID 27331819, 2016). "Collectively, through these intracellular and extracellular actions, S100A4 contributes to several hallmarks of cancer, including cell survival and proliferation, angiogenesis, invasion and metastasis, and tumor-promoting inflammation." (PMID 27127879, 2016). "The expression of S100A4 in primary tumor samples was analyzed by Western blot analysis, showing a significantly increased overall expression of S100A4 in tumors lacking AKT3 compared to controls." (PMID 26741489, 2016). "We observed that cells expressing mutant S100A4 are impaired in the tumor growth with reduced tumor weight, compared to the cell harboring WT S100A4." (PMID 27793047, 2016). "Conversely, when silencing S100A4 by shRNA technology, a dramatic decrease in tumour development of the pancreatic MiaPACA-2 cell line was observed." (PMID 27278648, 2016). "Among the known molecules that are engaged in stimulating the metastatic spread of tumor cells is the S100A4 protein." (PMID 25884510, 2015). "The prometastatic calcium-binding protein, S100A4, is expressed in endothelial cells, and its downregulation markedly suppresses tumor angiogenesis in a xenograft cancer model." (PMID 26029719, 2015). "It is of considerable importance that gene expression of S100a4 and S100a11 was up to 34-fold induced in tumours of EGF transgenic mice, however expression of S100a1 was repressed." (PMID 25872475, 2015). "The data in this paper clearly suggests that blocking S100A4 activity, using the 6B12 antibody, should hamper the pro-metastatic activity of the tumor microenvironment by restoring the T-cell polarization balance." (PMID 25884510, 2015). "Based on this, we propose that S100A4-induced alterations of the Th1/Th2 polarization balance in the tumor microenvironment can therefore promote tumor progression." (PMID 25884510, 2015).
tumor (continued). "Altogether, the NBD peptide is a potent inhibitor for tumor angiogenesis, and is the first example of an anticancer peptide drug developed on the basis of an endothelial S100A4-targeted strategy." (PMID 26029719, 2015). "Inhibition of S100A4 signaling by S100A4 shRNA or a neutralizing monoclonal antibody against S100A4 dramatically decreases tumor development of the pancreatic MiaPACA-2 cell line injected subcutaneously in nude mice." (PMID 25677816, 2015). "SAA1 and SAA3 are effectors of the metastasis-promoting functions of the small calcium binding protein S100A4, providing a link between inflammation and tumour progression." (PMID 26512722, 2015). "S100A4 is known as an inducer of inflammatory processes and has been shown to attract T-cells to the primary tumor and to the pre-metastatic niche." (PMID 25884510, 2015). "A large body of evidence supports the calcium-binding protein S100A4 role in control of invasion and metastasis in many invasive tumours." (PMID 25598217, 2015). "The anti-S100A4 monoclonal antibody, 6B12, exhibited anti-metastatic activity by blocking T-cell infiltration in a tumor graft mouse model." (PMID 25884510, 2015). "Quantitative analysis of FN transcripts in the lungs confirmed increased FN gene expression in tumor-bearing mice compared to control mice injected only with S100A4(+/+) MEFs." (PMID 25884510, 2015). "To further characterize the changes that occur in the pre-metastatic lungs we compared the cytokines released in pre-metastatic lung organ cultures from S100A4(+/+) MEF versus S100A4(-/-) MEF boosted tumor-bearing mice using a cytokine antibody array." (PMID 25884510, 2015). "One of these genes is S100A4, which is known to promote invasion and metastasis in different tumor cells." (PMID 25738360, 2015). "Mice injected with stable S100A4-downregulated cells showed a significant delay in tumor development." (PMID 25677816, 2015). "Ambartsumian and co‐workers have shown that S100A4 protein mediates the attraction of T cells in vitro and that S100A4 production by cancer cells stimulates tumor infiltration by T cells." (PMID 26734465, 2015). "By utilizing this function S100A4 modifies the tumor microenvironment and pre-conditions secondary organs to accept tumor cells." (PMID 25884510, 2015). "In conclusion, the present results show the importance of endothelial S100A4 expression in tumor angiogenesis." (PMID 23929008, 2014). "Several recent studies have evaluated S100A4 as a therapeutic target in preclinical models, and some have found that S100A4 is negatively correlated with cell growth in tumor cells." (PMID 25310523, 2014). "The quantification of S100A4 mRNA in plasma samples is suited as a diagnostic tool for CRC metastasis, which allows early therapeutic interventions to reduce S100A4 in tumor tissues, and in turn disease progression." (PMID 24952599, 2014). "For more than 10 years, many studies have shown that S100A4 plays an important role in tumor metastasis." (PMID 24885536, 2014). "Although the clinical correlation between S100A4 expression and tumor metastasis is more conclusive, future studies are warranted to define the relevant interactions between S100A4 and its binding partners." (PMID 25310523, 2014). "S100A4, a member of the S100 family of EF-hand calcium-binding proteins, is involved in the regulation of a variety of biological processes, including tumor progression and metastasis." (PMID 23929008, 2014). "The authors reported that after co-injection of mouse mammary CSML100 tumor cells with S100A4 (+/+) fibroblasts mice developed metastatic tumors in the lung." (PMID 24978438, 2014). "The involvement of S100A4 in the promotion of tumor metastasis has been demonstrated by several approaches." (PMID 23929008, 2014).
tumor (continued). "The S100 protein family has attracted increasing attention in the field of cancer research; in particular, S100A4 reportedly contributes to various aspects of tumor progression, including cell motility, metastasis and angiogenesis." (PMID 25310523, 2014). "Using B16BL6 tumor tissues little expressing S100A4, we stained tumor microvessels for CD31 and S100A4 and found that there are subpopulations of endothelial cells in tumors, S100A4-positive and –negative ones." (PMID 23929008, 2014). "S100A4 expression in cancer affects many disease related cellular responses, like angiogenesis, cell motility, invasion, and cell survival, contributing to tumor progression and metastasis formation." (PMID 24952599, 2014). "Researchers have investigated S100A4 for its involvement in multiple aspects of tumor progression, such as proliferation, apoptosis, cell motility, extracellular matrix remodeling and angiogenesis." (PMID 25310523, 2014). "mRNA levels of β-catenin and S100A4 were correlated with the IHC findings at the tumor invasive margin." (PMID 23783026, 2013). "We evaluated the expression of E-cadherin, β-catenin, and S100A4 by immunohistochemistry (IHC) in 333 CRC tissues from the tumor center and invasive margin." (PMID 23783026, 2013). "S100A4 has also been shown to be involved in the control of tumor growth in human cancer, and to be a potential prognostic marker." (PMID 23667563, 2013). "On the other hand, most S100A4 expression studies have focused on tumours at multiple stages; there have also been several previously published reviews on this topic." (PMID 24188373, 2013). "In vivo experiments have shown evidence of S100A4 direct involvement in tumor progression and metastasis." (PMID 23476112, 2013). "Conversely, when silencing S100A4 by shRNA technology, a dramatic decrease in tumor development of the pancreatic MiaPACA-2 cell line was observed." (PMID 24023743, 2013). "Keeping in mind the angiogenic role displayed by S100A4, we analyzed the formation of new microvascular vessels into the tumor in order to give a possible explanation of the dramatic observed tumor increase." (PMID 24023743, 2013). "Among the 85 GC tissue specimens from young patients screened for S100A4 protein expression, 53 (62.35%) exhibited S100A4 overexpression, in which immunostaining was observed in the cytoplasm or the nucleus of the tumor cells." (PMID 23760193, 2013). "S100A4 protein was detected in 18 (21.18%) out of the 85 non-tumor mucosal samples obtained from young patients." (PMID 23760193, 2013). "Our findings indicated that 5C3 regressed tumor vasculature and inhibited in part tumor growth, pointing to a critical role of extracellular S100A4 during tumor progression." (PMID 24023743, 2013). "S100A4, a member of the S100 calcium-binding protein family secreted by tumor and stromal cells, supports tumorigenesis by stimulating angiogenesis." (PMID 24023743, 2013). "The purpose of the present study was to investigate the cellular mechanism of action of S100A4 in EC to better understand the characteristics, function and therapeutic applicability of this protein in the angiogenic process and tumor development." (PMID 24023743, 2013). "The calcium-binding protein S100A4 also plays an important role in the metastatic journey of tumor cells by influencing several steps in the metastatic cascade, including migration, invasiveness, and angiogenesis." (PMID 24379889, 2013). "Inconsistently other results, S100A4 was also related to lymphocyte infiltration, which protects tumor progression and destroys tumor budding." (PMID 23783026, 2013). "In this line of in vivo evidences, we observed that the stable silencing of S100A4 with shRNA in MiaPACA-2 cells dramatically inhibited the tumor growth." (PMID 24023743, 2013). "The present study demonstrates the prognostic significance of S100A4 overexpression in the tumor cells of young GC patients for the first time." (PMID 23760193, 2013).